IL6 (interleukin 6)
Diseases named in the same sentence as IL6 in open-access papers (continued):
Sharing a sentence is not in itself a finding about the gene and the disease.
chorioamnionitis (continued). "We also found an association of histologic chorioamnionitis with higher maternal serum IL-6 levels at delivery as well has higher cord serum levels of IL-6 and IL-8." (PMID 22412842, 2012). "Our analysis included inflammatory mediators reported to be associated with chorioamnionitis, preterm labor, and fetal inflammatory response syndrome such as IL-1α, IL-1β, IL-6, TNF-α, S100A8, and S100A9." (PMID 22952869, 2012). "Also, we previously reported that IL-1β and IL-6 are responsible for chorioamnionitis-associated PTB and weakened fetal membrane through intense generation of extracellular matrix degrading metalloproteases." (PMID 35464466, 2022). "In pregnancies with PTL, both intra-amniotic infection and sterile inflammation were associated with elevated concentrations of IL-6 in the cervical fluid (intra-amniotic infection: median 587 pg/mL; sterile intra-amniotic inflammation, median: 590 pg/mL; without inflammation, median: 136 pg/mL)." (PMID 35118439, 2021). "Fetal plasma IL-6 levels have also been shown to be significantly associated with inflammatory lesions in the chorioamnion, leading to the conclusion that funisitis and chorioamnionitis are histological markers of FIRS." (PMID 25520716, 2014). "Elevated levels of cord blood proinflammatory cytokines (IL‐1β, TNFα, and IL-6) have also been associated with preterm birth, one of the most common causes of neonatal morbidity and mortality, as well as chorioamnionitis, brain white matter damage, and chronic lung disease in preterm infants." (PMID 20940111, 2011). "In the context of intrauterine infection and chorioamnionitis, maternal immune activation may cause tissue injury and trigger maternal inflammatory/immune responses, releasing a plethora of effector molecules, with IL‐6 and IL‐8 having one of the key roles." (PMID 39575516, 2024). "Intra-amniotic infections, such as funisitis or chorioamnionitis, are associated with higher levels of inflammatory cytokines, such as tumor necrosis factor alpha (TNFα) and interleukins (IL), including IL-1beta (IL-1b), IL-6, and IL-8 in amniotic fluid, cord blood, and newborn blood samples." (PMID 35626879, 2022). "Elevated cord blood IL-6 level often correlates with the tissue changes evidenced in chorioamnionitis and funisitis, connecting the laboratory findings with inflammatory processes at the microscopic level." (PMID 41010644, 2025). "The monitoring of cervically acquired inflammatory markers such as IL-6 has been reported to be reliable for the assessment of chorioamnionitis." (PMID 41150786, 2025). "Multiple clinical and animal studies have helped to better characterise this pathological inflammatory response in chorioamnionitis, demonstrating the presence of elevated levels of interleukins (IL)−1β, IL-6, IL8, IL-10 in amniotic fluid." (PMID 40464837, 2025). "Animals from the 8 d Sterile Chorioamnionitis Group also had significantly increased placental mRNA for IL6 (mean dCt difference = 2.51; 95% CI 4.95 to 0.07, p = 0.044) compared to the Negative Control Group." (PMID 40464837, 2025). "To investigate the effect of BD2 on the amniotic membrane in patients with chorioamnionitis, we compared the levels of inflammatory cytokines, including IL-6 and IL-1β, and anti-inflammatory cytokines such as IL-10 between the patient and normal groups." (PMID 40076749, 2025). "At present the gold standard to confirm suspected chorioamnionitis is amniocentesis with culture and Gram stain (sensitivity 65%, specificity 99%, AUC 0.82), or measurement of inflammatory markers including IL-6 (AUC of 0.84)." (PMID 40464837, 2025). "In 66% of included patients, histological chorioamnionitis was diagnosed and the Il-6 level of 19.5 pg/mL was the best cut-off point for predicting chorioamnionitis." (PMID 41470233, 2025). "In in vitro studies, ureaplasma had similar upregulate effects in TNFα, IL-1β, IL-6 and IL-8, which were commonly associated with PROM or chorioamnionitis." (PMID 38570745, 2024).
chorioamnionitis (continued). "However, the focus on elective cesarean delivery did confer the advantage of reducing the variability of the CB plasma cytokines, because higher cord levels of both IL-1 and TNF-α are seen in chorioamnionitis and long, difficult labors may impact tissue IL-6 levels." (PMID 39683596, 2024). "In the early stages of chorioamnionitis, infection and inflammation are limited to the chorion and amnion membranes, and IL-6 is released into the maternal blood, leading the mother to produce CRP." (PMID 37919654, 2023). "Histological chorioamnionitis has been correlated with increased cord blood IL-1β and IL-6, increased heart rate and decreased blood pressure in the first week after birth." (PMID 36994431, 2023). "That infant had the second-highest MCP-1 levels within the chorioamnionitis-positive cohort (mean of 2078 mg/dL) as well as elevated IL-6 and CRP values on day 1 (2946 pg/mL and 5.2 mg/dL, respectively)." (PMID 37606448, 2023). "High concentrations of IL-6 are present in amniotic fluid during the second and third trimester of pregnancy and increase in chorioamnionitis and preterm delivery." (PMID 37685739, 2023). "Intra-amniotic inflammation is defined by an elevation of the interleukin-6 (IL-6) concentration (IL-6 ≥2.6 ng/mL), and intra-amniotic infection is a combination of demonstrable microorganisms in the amniotic cavity and intra-amniotic inflammation." (PMID 36503654, 2023). "In the funisitis group, the concentrations of inflammatory cytokines, including IL-1b, IL-6, and IL-8, were significantly higher than in the chorioamnionitis and control groups." (PMID 35626879, 2022). "Among the cytokines, only IL-6 concentrations in the chorioamnionitis group were significantly higher than in the control group." (PMID 35626879, 2022). "We also investigated other pro-inflammatory cytokines involved in GBS-induced chorioamnionitis, including IL-6 and TNF-α." (PMID 35563368, 2022). "In contrast, in the cord blood of newborns in the chorioamnionitis group, only IL-6 and C5a, which are earlier indicators of infection, were significantly higher than in the control group." (PMID 35626879, 2022). "Various cytokines, such as IL-1, IL-6, IL-8, and tumour necrosis factor-α (TNFα), have been discovered to play a role in the pathogenesis of chorioamnionitis-induced foetal inflammation." (PMID 35453930, 2022). "TH, OSI, IL-1b, IL-6, and IL-8 concentrations were higher in the funisitis group than in the chorioamnionitis and control groups." (PMID 35626879, 2022). "IL-6 and IL-8 in cervical secretions can also predict PTL caused by intra-amniotic infection or chorioamnionitis." (PMID 35118439, 2021). "The optimum cut-off values for the prediction of chorioamnionitis were found to be 1389.82 pg/mL for IL-6, 21.17 pg/mL for TNF-α, and 172.53 ng/mL for MMP-8." (PMID 33800521, 2021). "In our study, we found that the MMP-8 test had better specificity than the IL-6 test for the detection of chorioamnionitis." (PMID 33800521, 2021). "Previous studies reported that when the mother had chorioamnionitis, interleukin-6 and interleukin-1β in cord blood increased to relax the vascular smooth muscle, causing tachycardia and hypotension in the newborn." (PMID 34648528, 2021). "During chorioamnionitis, the concentration of inflammatory mediators including IL-1β, IL-6, IL-8, MMP9 and TNFα in the amniotic fluid increases dramatically." (PMID 32636848, 2020). "We set out to evaluate the accuracy of maternal blood C-reactive protein (CRP), procalcitonin and interleukin 6 (IL6) in diagnosis of histological chorioamnionitis and/or funisitis (HCA/Funisitis) in PPROM." (PMID 32532314, 2020). "Monocytes from chorioamnionitis-exposed term infants with increased H3K4me3 modifications produced less IL-1β, IL-6, and IL-8 when stimulated with LPS." (PMID 32636848, 2020).
chorioamnionitis (continued). "An important finding was that IA plant sterol administration decreased the fetal systemic inflammatory response (circulatory IL-6 levels) during UP-driven chorioamnionitis." (PMID 31035616, 2019). "In predicting intra-amniotic infection, the AUC for plasma IL-6 was significantly lower than that for AF IL-6 (P < 0.001), but was not different from the AUC for serum CRP (P = 0.414)." (PMID 29743041, 2018). "We found that an elevated plasma level of IL-6 predicted intra-amniotic infection in women with preterm labor." (PMID 29743041, 2018). "In predicting intra-amniotic infection, the area under the curve (AUC) was significantly lower for plasma IL-6 than for AF IL-6 but was similar to that for serum CRP." (PMID 29743041, 2018). "Several studies have shown that increased levels of interleukin (IL)-6, matrix metalloproteinase (MMP)-9, and complement split products (C3a and C4a) in AF are associated with both intra-amniotic infection and preterm parturition." (PMID 29743041, 2018). "FIRS is defined by elevated interleukin-6 (IL-6) fetal plasma concentration in the presence of chorioamnionitis, PROM or preterm delivery." (PMID 28442989, 2017). "In the amniotic fluid, levels of IL-1β, IL-6, IL-8, TNFα, CCL3, 4, and 5 are elevated in women with threatened PTL, especially in the presence of intra-amniotic infection, as are IL-1β, IL-6, IL-8, TNFα, and CCL2 in the cervical fluid." (PMID 25741339, 2015). "Specifically, elevation of pro-inflammatory cytokines/chemokines such as IL-1β, Il-6, IL-8 and TNF-α within the AF and fetal membranes have been associated with preterm delivery and chorioamnionitis." (PMID 22253806, 2012). "Admission IL-6 and IL-8 levels were both significantly higher among those found to have histologic chorioamnionitis." (PMID 22412842, 2012). "Disease outcome was assessed by microbial culture, in situ detection of U. parvum in fetal and utero-placental tissues, grading of chorioamnionitis, and placental gene expression of IL-1α, IL-1β, IL-6, TNF-α, S100A8, and S100A9." (PMID 22952869, 2012). "C57BL/6 infected animals predominantly exhibited mild to moderate chorioamnionitis (P<0.0001), and a significant reduction in placental expression of IL-1α, IL-1β, IL-6, TNF-α, S100A8, and S100A9 compared to sham controls (P<0.02)." (PMID 22952869, 2012). "While cord blood Il-8 was elevated in cases of funisitis and both Il-6 and Il-8 were present with histologic chorioamnionitis, the inflammatory marker MMP-8, a leukocyte collagenase, was not correlated." (PMID 22114461, 2011). "Elevated Il-8 obtained from amniotic fluid was a correlate of intra-amniotic microorganisms and histologic chorioamnionitis, and similarly, bacterial 16s ribosomal RNA was found in placentas of women who had elevated Il-6 and Il-8." (PMID 22114461, 2011). "Chorioamnionitis was only weakly correlated with amniotic fluid IL-6, IL-8 and TNF-α (Spearman's ρ = 0.23, p<0.001, ρ = 0.22, p<0.001, and ρ = 0.17, p = 0.003, respectively)." (PMID 19668329, 2009). "In term vaginal deliveries, more signs of intrauterine inflammation were found than in elective CS: the prevalence of chorioamnionitis was higher (18 vs 4%, p = 0.02) and amniotic fluid concentration of IL-6 was higher (3.1 vs 0.37 ng/mL, p<0.001)." (PMID 19668329, 2009). "Other groups have observed that elevated IL-6, IL-8, M-CSF, and TNF-receptor 2 in the cervicovaginal fluid have been independently associated with acute histological inflammation of the fetal membranes (chorioamnionitis)." (PMID 41277827, 2025). "Indeed, both IL-6 and CXCL1 have been implicated in the pathogenesis of adverse pregnancy outcomes, including stillbirth, preterm labor, and chorioamnionitis, as has maternal infection/reinfection with naturally occurring AAV during pregnancy." (PMID 38950310, 2024). "DSC expression of IL6 during chorioamnionitis was previously reported." (PMID 38895127, 2024).
chorioamnionitis (continued). "Interleukin-6 is a proinflammatory cytokine expressed by T-cells and macrophages in response to infection or inflammation Elevated values have been found in cord blood in chorioamnionitis." (PMID 39227528, 2024). "Elevated amniotic IL-6 levels indicate intra-amniotic infection and PTB." (PMID 39791063, 2024). "Vaginal biomarkers have been proposed as a diagnostic tool for chorioamnionitis given the minimally invasive nature of collection and multiple studies showing a positive correlation between MIAC and the inflammatory proteins IL-6 and IL-8 in cervicovaginal fluid." (PMID 38001923, 2023). "Elevation in IL-6 levels is often found in cord blood of infants affected by maternal chorioamnionitis, suggesting leptin could be similarly impacted." (PMID 35197933, 2022). "We hypothesized that there would be a positive correlation between IL-6 and leptin with progressively increased levels in pregnancies complicated by maternal diabetes and chorioamnionitis." (PMID 35197933, 2022). "Based of microbial invasion of the amniotic cavity and intra-amniotic inflammation (interleukin-6 ≥ 3000 pg/mL), the women were divided into following groups: intra-amniotic infection, sterile intra-amniotic inflammation, colonization of the amniotic cavity, and negative amniotic fluid." (PMID 35332204, 2022). "IL-6 is increased during the active phase of delivery, significantly elevated in preterm birth compared to term delivery, and increased in neonates exposed to histologic chorioamnionitis." (PMID 36430355, 2022). "Clinically diagnosed chorioamnionitis and neonatal sepsis were associated with increased IL-6 but not leptin." (PMID 35197933, 2022). "In chorioamnionitis, local levels of cytokines such as IL-1, IL-6 and TNF-α are increased." (PMID 33648480, 2021). "While IL-6 does not stimulate contractions, the onset of labor causes a 1.5-fold increase in IL-6 compared to non-pregnant women, but the increases are greater in the context of chorioamnionitis, infection, or preterm birth." (PMID 34959801, 2021). "Chorioamnionitis is usually associated with Fetal Inflammatory Response Syndrome (FIRS), which is defined by increased systemic inflammatory cytokines (for e.g., interleukin-6) concentrations, funisitis, and fetal vasculitis, with possible secondary extensive damage of lungs and brain." (PMID 34682182, 2021). "To further investigate the association between S100A gene expression and risk groups, we identified a set of clinical conditions associated with chorioamnionitis and fetal inflammation, namely PTL/PPROM (spontaneous onset of delivery), HCA, FIRS and elevated CRP/IL-6." (PMID 32612607, 2020). "We then studied other pro-inflammatory cytokines that are involved in GBS infection and chorioamnionitis, namely IL-18, IL-6 and TNF-α, to evaluate whether they presented the same sexually dichotomous profile." (PMID 31197179, 2019). "In addition, chorioamnionitis is associated with the fetal inflammatory response syndrome (FIRS), which is characterized by increased IL-6 concentrations in fetal blood and is an independent risk factor for severe neonatal morbidity." (PMID 31035616, 2019). "Indeed, it has been shown that cord blood levels of interleukin (IL) 1β and IL-6 increase in neonates with chorioamnionitis." (PMID 30473713, 2018). "Similarly, our previous study found that serum CRP has a diagnostic performance similar to that of IL-6 and MMP-9 in AF for the detection of histologic chorioamnionitis." (PMID 29743041, 2018). "Our results suggest that the brain injury in fetuses exposed to chorioamnionitis could be mediated by circulating IL-6 and/or CCL2." (PMID 27596440, 2016). "Furthermore, IL-1β, IL-6, and IL-8 concentrations are increased in maternal plasma women with preterm premature rupture of the membranes and chorioamnionitis." (PMID 25741339, 2015). "IL-6 is increased in the umbilical blood of infants born to mothers with chorioamnionitis." (PMID 25741339, 2015).
chorioamnionitis (continued). "Finally, median cord levels of both IL-6 and IL-8 were significantly higher, particularly among those with Grade 2 histologic chorioamnionitis." (PMID 22412842, 2012). "However, by all kits we were able to identify that amniotic fluid from patients with chorioamnionitis contained significantly higher IL-6 concentrations than those from normal mid-trimester pregnancies." (PMID 18476141, 1997). "Furthermore, cord IL-6 concentrations were shown to increase approximately four-fold during labor compared to non-laboring cesarean deliveries, with an additional six-fold rise in cases with histologic chorioamnionitis." (PMID 41302151, 2025). "Interestingly, intraamniotic injection of IL6 in the NHP does not cause chorioamnionitis and preterm labor." (PMID 38895127, 2024). "The purpose of this study was to evaluate the association of two risk factors for impaired neonatal development, maternal diabetes and chorioamnionitis, with umbilical cord blood levels of two hormones that may contribute to long-term neurodevelopmental outcomes, leptin and IL-6." (PMID 35197933, 2022). "We utilized a high risk pregnancy cohort enriched with perinatal morbidities of interest to test the hypothesis that there is a positive correlation between cord blood IL-6 and leptin with progressively increased levels in pregnancies complicated by maternal diabetes and chorioamnionitis." (PMID 35197933, 2022). "This prevented us from analyzing whether the vaginal fluid IL-6 and TNF-α concentrations changed on the last day before labor, because there is a higher risk for the development of chorioamnionitis when there is a longer latency period in the rupture of the membranes." (PMID 33800521, 2021). "Additionally, IL-6 is hypothesized to play an important role during infection induce chorioamnionitis by activating immune cells within the choriodecidua layer." (PMID 32848846, 2020). "Importantly, we found that serum CRP (the most used infection/inflammation marker) has a predictive power similar to that of plasma IL-6 for predicting intra-amniotic infection and is similar to that of plasma IL-6 and AF IL-6 for predicting imminent preterm delivery." (PMID 29743041, 2018). "In chorioamnionitis, diminished IL-10 levels may provide an ineffective counter regulatory response to elevated maternal prostaglandin stimulated by the pro-inflammatory cytokines IL-1, IL-6 and TNF." (PMID 15723707, 2005). "The IL-6 bedside test had significantly higher sensitivity, specificity, NPV, and overall accuracy than the clinical and laboratory parameters of chorioamnionitis." (PMID 41470233, 2025). "Maternal cytokines were quantified by multiplex immunoassay, and fetal inflammatory exposure (Triple I) assessed using histological chorioamnionitis (HCA), cord blood haptoglobin, and IL-6." (PMID 40964021, 2025). "During expectant management, chorioamnionitis is typically monitored using serum inflammatory markers (e.g., leukocyte count, CRP), though cervical interleukin-6 (IL-6) has emerged as a promising local marker." (PMID 41150786, 2025). "We performed targeted analyses utilising Random Forest Algorithm of the same eight cfRNA targets (IL1α, IL1β, IL6, IL8, IL10, IL18, CD14, TNFα) used in the chorioamnionitis study." (PMID 40464837, 2025). "Antenatal exposure to cytokines, interleukin-6 [IL-6], interleukin-8 [IL-8], tumor necrosis factor-alpha [TNF-a], interleukin-1beta [IL-1b], is a risk factor for developing BPD and might predispose the subset of neonates exposed to chorioamnionitis prenatally to the development of BPD." (PMID 39795932, 2024). "Main findings of the study are that during IUI the major producers of IL6 are the decidua stroma cells and amnion mesenchymal cells in both preterm Rhesus macaque model of LPS-induced IUI and in preterm human subjects with chorioamnionitis." (PMID 38895127, 2024).